CHRM1 (cholinergic receptor muscarinic 1)
Diseases named in the same sentence as CHRM1 in open-access papers (continued):
Sharing a sentence is not in itself a finding about the gene and the disease.
colorectal cancer (1 paper, 2022). A primary or metastatic malignant neoplasm that affects the colon or rectum. "Based on these considerations, we explored the relationship between reduced expression of CHRM1, increased expression of CHRM3, and the expression levels of genes commonly mutated in colorectal cancer." (PMID 35370785, 2022). "Our findings suggest an important relationship exists between CHRM1/M1R and β-catenin signaling in colorectal cancer." (PMID 35370785, 2022).
dementia (1 paper, 2024). Loss of intellectual abilities interfering with an individual's social and occupational functions. "Proteins most highly increased in dementia cases included phospholipid transporter TMEM30A, calcium channel modulator ORAI2, and various muscarinic cholinergic receptors (CHRM1, CHRM3)." (PMID 39107789, 2024). "P-M26 featured muscarinic cholinergic receptors CHRM1 and CHRM4, which have both demonstrated promise as synaptic targets for cognitive and behavioral symptoms in dementia." (PMID 39107789, 2024).
Dysmenorrhea (1 paper, 2025). Pain during menstruation that interferes with daily activities. "Six essential oil components could be associated with chronic pain, acute pain, musculoskeletal pain, visceral spasms, and dysmenorrhea by acting on four protein targets, including CHRM1, PTGS1, PTGS2, and SLC6A2." (PMID 40729010, 2025).
esophageal cancer (1 paper, 2024). A primary or metastatic malignant neoplasm involving the esophagus. "The axes formed by choline O-acetyltransferase (CHAT) and muscarinic receptors CHRM1, 3, and 5 are associated with lower survival in multiple cancers, including liver and esophageal cancer." (PMID 38723607, 2024).
Hypertension (1 paper, 2022). The presence of chronic increased pressure in the systemic arterial system. "In the PPI network, a total of 14 targets, such as TNF, CHRM1, ACE, IL10, PTGS2, REN, and F2, were the hub targets of MVO for treating hypertension." (PMID 35308213, 2022). "Moreover, the results highlighted the idea that MVO could regulate the expression levels of targets, especially for TNF, CHRM1, ACE, IL10, PTGS2, REN, and F2, as well as neuroactive ligand–receptor interaction, the calcium signaling pathway, and PI3K-Akt signaling pathway to treat hypertension." (PMID 35308213, 2022).
ischemic stroke (1 paper, 2021). A stroke disorder caused by obstruction of blood flow to the brain, due to thrombotic (local blood clot formation) or embolic (due to a blood clot or other material traveling from another site) event. "Studies on CHRM1 and FOS related to ischemic stroke are very rare, but this just provides new ideas for us to study ischemic stroke." (PMID 34603472, 2021).
lung carcinoma (1 paper, 2022). "We compared the levels of CHRM1 expression in PC-3, LNCaP, human PCa cell line DU145, RWPE-1, and the lung cancer cell line A549 via WB analysis." (PMID 35720225, 2022).
lymphoid cancer (1 paper, 2024). "While cell lines from certain tissues seem to be equally inhibited by top GPCR drugs (e.g., lung), others are sensitive to specific GPCR drugs, such as lymphoid cancer cells, which are particularly inhibited by DRD2, CHRM1, CHRM2, HTR1A, and HTR2A antagonists." (PMID 38723607, 2024).
myopia (1 paper, 2013). "Comparison between muscarinic receptor mutants showed that M1 (Chrm1), M4 (Chrm4) and M5 (Chrm5) mutants had significantly higher myopia in the lens-treated eyes than did M2 and M3 mutants." (PMID 23649821, 2013).
Optic neuropathy (1 paper, 2024). "Consequently, optic neuropathy resulting from elevated IOP may lead to reduced CNS expression of Chrm1 in BXD mice and the subsequent negative correlation observed in systems genetics analysis of their whole eyes." (PMID 39130374, 2024).
psychotic disorder (1 paper, 2023). An abnormal condition of the mind that involves a loss of contact with reality. "Another finding from the study of 123I-IDEX to CHRM1/CHRM4 binding in psychosis was that lower levels of binding in the DLPFC was related to worse verbal learning and memory scores whereas lower hippocampal binding predicted worse delayed recall." (PMID 36909280, 2023).
tumor (20 papers, 2014 to 2026). "BN-PAGE analysis showed that Chrm1 expression was effective in causing a plastic change in the OXPHOS system of the tumor cells." (PMID 37274741, 2023). "In contrast, during the later stages of cancer progression, the denervation of parasympathetic nerves or the inhibition of muscarinic acetylcholine receptor 1 (CHRM1) obstructs the metastasis of tumor cells." (PMID 41601691, 2026). "provided robust evidence through quantitative measurements of the effect of vagotomy on tumor burden and identified CHRM1 as the key receptor suppressing tumor growth." (PMID 41556039, 2026). "CHRM1 agonism improves tumor cell invasion into the pelvic lymph nodes (LN), while CHRM1 antagonists effectively suppress LN metastasis." (PMID 41556039, 2026). "Simultaneously, differentiation- and immune-activating signals such as CSF1, TNFSF9, KITLG, EHF, and CHRM1 were downregulated, potentially modulating tumor immune escape and proliferation in a context-dependent manner." (PMID 41009714, 2025). "These strategies will become increasingly important because they will allow the targeting of individual genes (i.e., CHRM1, ADβR2) to slow tumor growth and overcome treatment resistance." (PMID 33322770, 2020). "The unanticipated findings regarding the impact of Chrm3 and Chrm1 knockout on AOM-induced colon neoplasia provided an opportunity to explore M3R-regulated changes in tumor gene expression." (PMID 24694019, 2014). "Even more surprising were the outcomes in dual KO mice; tumor number and volume were only slightly reduced compared to those in WT and Chrm1-/- mice." (PMID 24694019, 2014). "We were further surprised to observe that combined Chrm3 and Chrm1 knockout mitigated reductions in tumor number and size observed with Chrm3 knockout alone." (PMID 24694019, 2014). "Furthermore, tumor macrophages stimulated angiogenesis via activation of CHRM1 and CHRM2, which triggered the arginine metabolic pathway." (PMID 41516199, 2025). "Mechanism dissection reveals that the cholinergic receptor muscarinic 1 (CHRM1) receptor expressed by tumor cells is responsible for the cholinergic suppressive effect via modulating mitogen-activated protein kinases (MAPK) and phosphatidylinositol-3-kinase (PI3K)-AKT pathways." (PMID 36230914, 2022). "In PDAC, enhanced cholinergic signals could directly inhibit MAPK/EGFR, and PI3K/AKT pathways which were mediated by type 1 muscarinic receptors (CHRM1), but also could indirectly suppress tumor progression by inhibiting tumor stem cell transformation." (PMID 34572820, 2021). "In particular, the expression of the CHRM1, CHRNA2, CHRNA4, CHRNA6, CHRNA7, and CHRNB2 genes was increased in samples from the tissue of the anterior edge of the tumor." (PMID 38393158, 2024). "Using RNA sequencing studies, the authors showed that Chrm1 signals perturb EGFR/MAPK and PI3K/AKT cascade in cancer cells to inhibit tumor growth." (PMID 32477953, 2020). "Instead, we were surprised to observe that Chrm1 gene ablation alone did not alter tumor formation." (PMID 24694019, 2014). "Based on our previous findings regarding the interplay of M1R and M3R in gastric function, we hypothesized that compared to the effects of Chrm3 gene ablation alone, concurrent ablation of Chrm3 and Chrm1 might further attenuate, or even abolish, AOM-induced tumor formation." (PMID 24694019, 2014). "While the expression of many AChRs was not altered in comparison to the cellular tumor, we did find significant upregulations in the expression of CHRNA7, CHRNB2, CHRM1, and CHRM3 in these areas." (PMID 31590360, 2019).
cancer (12 papers, 2018 to 2026). A tumor composed of atypical neoplastic, often pleomorphic cells that invade other tissues. "Activation of Chrm1 also induced the migration and invasion of two cancer cell lines, HepG2 and SMMC-7721, via the PI3K/Akt pathway." (PMID 38139000, 2023). "Several reports have indicated the involvement of Chrm1 in both the promotion and inhibition of cancer growth." (PMID 38139000, 2023). "Five hypermethylated regions were in genes previously associated with cancer (TRAP1, SLC38A3, CHRM1, EDN2, and PROX1), while six hypomethylated regions were in genes previously associated with cancer (NUMBL, ALDH1B1, FTCD, FASTKD2, FAM96A, and ARHGAP15)." (PMID 36474183, 2022). "Certain cancers overexpress certain receptors and its mediation is normally related to other effectors, such as EGFRs and CHRM1–5." (PMID 35565451, 2022). "Lastly, we used the relationship between expression levels of genes with a significant relationship to CHRM1 expression to identify gene ontology (GO) terms and pathways of importance to cancer progression." (PMID 35370785, 2022). "Chrm1 activation was also shown to suppress cancer stem cells (CSCs), which is an additional mechanism by which cholinergic signals suppress tumors." (PMID 32477953, 2020). "Comparing HCC in the choline deficient model and choline supplemented model, significant methylation differences were seen in 11 genes previously associated with cancer (hypermethylation of TRAP1, SLC38A3, CHRM1, EDN2, and PROX1; hypomethylation of ALDH1B1, FTCD, FASTKD2, FAM96A, and ARHGAP15)." (PMID 36474183, 2022). "Overall, the Chrms, especially the Chrm1 and Chrm3, appear as promising targets for cancer therapy." (PMID 32477953, 2020). "Comparing muscarinic receptor subtype expression levels in adenocarcinoma vs. normal colon samples, we consistently observed reduced CHRM1, CHRM2, and CHRM4 and increased CHRM3 RNA levels (log2fc normal relative to cancer tissue)." (PMID 35370785, 2022).
adenocarcinoma (3 papers, 2014 to 2023). A common cancer characterized by the presence of malignant glandular cells. "We found CHRM1 expression was downregulated in adenocarcinomas and CHRM1 expression levels correlated with changes in the expression of β-catenin signaling pathway genes and their downstream targets." (PMID 35370785, 2022). "Colons from all Chrm1-/- mice contained at least one adenocarcinoma." (PMID 24694019, 2014).
neurodegenerative disease (3 papers, 2022 to 2023). A disorder of the central nervous system characterized by gradual and progressive loss of neural tissue and neurologic function. "Overall, the loss of Chrm1 signaling mediated brain region-specific alterations of the OXPHOS proteome and its supramolecular assembly indicates functional relevance in neurodegenerative disease." (PMID 37293125, 2023). "Therefore, CHRM1 has been postulated to be an important therapeutic target for neurodegenerative diseases, specifically AD." (PMID 37293125, 2023). "The component-target-disease network diagram revealed that the essential oil compositions in leaves of C. grandis ‘Tomentosa’ could treat tumors, immune diseases, neurodegenerative diseases and respiratory diseases, which were highly related to CHRM1, PTGS2, CASP3, MAP2K1 and CDC25B." (PMID 35702766, 2023).
infection (2 papers, 2015 to 2022). The state of being infected such as from the introduction of a foreign agent such as serum, vaccine, antigenic substance or organism. "After adjustment for the potential confounders, sex, age, and time since infection, we found in addition to CHRM5-Ab significant differences with higher levels of AABs against CHRM1 and F2R/PAR-1 while lower levels of ADRB1, CHRNA1, and EDNRA in PCS/ME/CFS than in PCS/non-ME/CFS groups." (PMID 36238301, 2022).
CHRM1 also shares sentences with these, for which no sentence is quoted: peripheral neuropathy (7 papers); Hepatic fibrosis (4); neuropathy (4); diabetes (3); diabetic neuropathy (3); epilepsy (3); insomnia (3); chronic obstructive pulmonary disease (2); Dyskinesia (2); glioblastoma (2); Sensory neuropathy (2); airway hyperresponsiveness (1); amnesia (1); amyloid (1); Ataxia (1); atherosclerosis (1); attention deficit-hyperactivity disorder (1); bipolar disorder (1); breast carcinoma (1); cardiovascular diseases (1); CNS tumor (1); cognitive disorder (1); colitis (1); colon adenoma (1); delirium (1); demyelinating disease (1); demyelination (1); Encephalopathy (1); ependymoma (1); fibrosis (1).
A further 28 diseases each share a sentence with CHRM1 in 1 paper.